BTG3 (BTG anti-proliferation factor 3)
Diseases named in the same sentence as BTG3 in open-access papers (continued):
Sharing a sentence is not in itself a finding about the gene and the disease.
tumor (39 papers, 2001 to 2025). "Overexpression of BTG3 K41R alone inhibited the proliferation and colony formation of cancer cells, indicating that the K41R mutation didn’t affect the anti-tumor effect of BTG3." (PMID 38777825, 2024). "Specific to genistein, such reduced methylation was also seen in other tumor suppressor genes, such as B-cell translocation gene 3 (BTG3) and Ras association domain family 1 (RASSF1A)." (PMID 38068715, 2023). "To further validate the role of BTG3 in regulating tumor angiogenesis, we sought to engineer a Btg3-deficient tumor microenvironment by genetic ablation of Btg3 in mice." (PMID 33311481, 2020). "Recent investigations have indicated that BTG3 acts as a tumor suppressor against the progression of cancer and loss of BTG3 expression is frequently accompanied by tumor development in several different cancers." (PMID 34466474, 2019). "A genomic microarray analysis showed that numerous tumor-associated signaling pathways and oncogenes were altered by BTG3 knockdown." (PMID 29270670, 2018). "In vitro loss- or gain-of-function studies demonstrated that BTG3 might function as a tumor suppressor in HCC." (PMID 35342408, 2022). "Taken together, these data suggest that BTG3 can be a “landscaping” tumor suppressor, the loss of which may produce a microenvironment which favors tumor growth and spread." (PMID 33311481, 2020). "Collectively, these data indicate that loss of Btg3 drives a pro-angiogenic and pro-tumorigenic microenvironment which could also possibly promote tumor metastasis." (PMID 33311481, 2020). "Taken together, the results of these analyses further support a role of BTG3 in the regulation of tumor angiogenesis, whose loss may promote disease progression and dampen patient survival." (PMID 33311481, 2020). "In HER2-positive disease, our findings associate genes such as ARG2, S100A1, MT2A, EIF4EBP1, KLF4, BTG3, and BAG1 to be associated with favourable prognosis through their roles in metabolic regulation, oxidative stress mitigation, and tumour suppression." (PMID 41007296, 2025). "The gene B cell transposition gene 3 (BTG3) is recognized as a tumor suppressor, known to inhibit cell cycle progression and cell proliferation." (PMID 39113685, 2024). "The representative images showed that the expression of TRIM65 in ccRCC tumor tissues was much higher while the BTG3 protein levels were lower than the adjacent normal kidney tissues, which was further confirmed by the results of the IHC scores." (PMID 38777825, 2024). "BTG3, a candidate tumor suppressor, prevents cell proliferation, induces apoptosis, and mediates cell cycle in various tumors." (PMID 36815904, 2023). "Compelling evidence has unraveled the tumor-suppressive properties of BTG3 in numerous tumors: for instance, overexpression of BTG3 prevents the GC cell invasion." (PMID 36815904, 2023). "B cell transposition gene 3 (BTG3) is reported to be a tumor suppressor and suppresses proliferation and cell cycle progression." (PMID 36186486, 2022). "In contrast, the mice injected cells treated with miR-106b-5p had more considerable tumor burden than controls and displayed higher expression for Ki67, PCNA, Bcl-xL, and cyclin E1, along with a lower expression for BTG3 in tumor tissues relative to controls." (PMID 35342408, 2022). "In previous studies, BTG3 has been identified as a candidate tumor suppressor gene that plays an important role in tumor growth and metastasis." (PMID 35342408, 2022). "In vivo, ectopic expression of BTG3 suppresses angiogenesis in xenograft tumors; and syngenic tumor growth and metastasis were enhanced in Btg3-null mice." (PMID 33311481, 2020). "B cell translocation gene 3 (BTG3) inhibition is a promising strategy by tumor cells to decrease the efficacy of radiotherapy." (PMID 32612456, 2020). "Second, BTG3 acts as a tumor suppressor that is required for CHK1 ubiquitination and maintaining genomic stability." (PMID 32357935, 2020).
tumor (continued). "Concerning the expression increase of BTG3 as a tumor suppressor gene, what it is pioneering in this study is to suggest another action mechanism of genistein." (PMID 34466474, 2019). "Compared to the relatively stronger cytoplasmic expressions of BTG3 in adjacent normal colorectal tissues, BTG3 expressed in tumor tissues with mostly moderate to weak cytoplasmic staining." (PMID 29270670, 2018). "The tumor volume and weight of both parental cells were larger and heavier than those of BTG3 transfectants by ruling, weighting and capacity measurement respectively (p<0.05)." (PMID 28407690, 2017). "We found that siRNA-mediated knockdown of FBXL5 or BTG3 significantly restored the invasive abilities and reduced the anti-tumor activity of cisplatin in iASPP- or miR-20a-silenced CC cells." (PMID 28399926, 2017). "BTG3 overexpression inhibited tumor growth of SW620 cells by suppressing proliferation and inducing apoptosis." (PMID 28407690, 2017). "Taken together, these data indicate that FBXL5 and BTG3 serve as tumor suppressors in CC cells, and miR-20a-FBXL5/BTG3 signaling is responsible for iASPP-induced EMT and cisplatin resistance." (PMID 28399926, 2017). "Here we delineated further the effects of the loss of BTG3 and demonstrated its role in safeguarding the AKT-GSK3β pathway, and, by crosstalk with the Wnt/β-catenin pathway, its role as a barrier to tumor progression." (PMID 25569101, 2015). "To determine the role of BTG3 in tumor suppression in a more physiological setting, we performed xenograft studies by implanting the PC3-TR (control) or PC3-ovBTG3 cells subcutaneously into immunosuppressed nude mice." (PMID 25569101, 2015). "Of the 188 tumor tissue sections (from 94 cases) and 20 normal/adjacent normal tissue sections (from 20 cases) examined, significant reduction in BTG3 staining was found in tumor tissues compared with normal tissues (P=0.03)." (PMID 25569101, 2015). "BTG3 has been shown to be a candidate tumor suppressor gene through its inhibitory activity on E2F1 causing negative regulation of cell cycle." (PMID 26198328, 2015). "Real-time quantitative PCR (qPCR) analysis for expression levels showed relatively low levels of BTG3 expression in tumor samples and RCC cell lines of A498, ACHN, and HEK-293 compared to normal tissue samples and HK-2 cells." (PMID 26198328, 2015). "The tumor volume and weight of both parental cells were larger and heavier than those of their BTG3 transfectants by ruling and weighting respectively (p < 0.05)." (PMID 25904053, 2015). "Downregulation of BTG3 was found in human cancers, implicating a possible role as a tumor suppressor." (PMID 25569101, 2015). "In this study, we provide evidence that BTG3 plays an important suppressive role in HCC progression especially tumor cell proliferation, invasion and cell cycle progression." (PMID 24147003, 2013). "Mechanistically, B cell translocation gene 3 (BTG3) was identified as a direct downstream target of miR-519c-3p, which acts as a tumor promoter in regulating HCC growth and metastasis by targeting BTG3 and may become a new therapeutic target for HCC." (PMID 38584703, 2024). "Besides, BTG3 was known as a tumor suppressor in many tumors, which is critical in cell proliferation." (PMID 38777825, 2024). "Our findings show that miR106b-5p levels were reduced post treatment with pembrolizumab, and these reduced levels could promote BTG3 expression that could lead to the apoptosis of cancer cells and reduce tumor growth." (PMID 39766101, 2024). "Since we’ve proved that TRIM65 can directly bind to BTG3 and facilitate its degradation via K48-linked ubiquitination, then we designed and performed rescue assays to confirm the role of TRIM65-regulated BTG3 degradation on the proliferation of tumor cells as well as the cell cycle." (PMID 38777825, 2024).
tumor (continued). "Moreover, in xenograft mice, baicalein prevented tumor growth, decreased Ki67-positive cells, activated BTG3, and inhibited the PI3K/AKT pathway, thus activating ERS and increasing apoptotic cells." (PMID 36815904, 2023). "As a result, more Luc-positive cancer cells were detected in tumor-bearing Btg3−/− mice than in WT." (PMID 33311481, 2020). "In this study, we first screened out TNBC specific lncRNA Lnc-BTG3-7:1, which sustained tumor progress, and this TNBC specific lncRNA and its target C21ORF91 gene were involved in Wnt/β-catenin and MAPK pathways, which were associated with cancer cell progress." (PMID 33585557, 2020). "In this study, we identified a TNBC specific lncRNA Lnc-BTG3-7:1, which sustained tumor progress." (PMID 33585557, 2020). "Therefore, it can be deduced that one of the pathways for anti-cancer action of genistein is through BTG3 as a tumor suppressor gene with anti-proliferative properties." (PMID 34466474, 2019). "Previous studies have indicated that BTG3 is a candidate tumor suppressor gene in various cancers." (PMID 29270670, 2018). "Finally, the in vivo effect of BTG3 overexpression on tumor growth was determined in nude mice bearing CRC cells." (PMID 28407690, 2017). "Although it connects two major growth-regulatory pathways functionally and is downregulated in human cancers, whether and how BTG3 acts as a tumor suppressor remain largely uncharacterized." (PMID 25569101, 2015). "Till now, only two recent papers have discussed the function of BTG3 in tumor." (PMID 24147003, 2013). "Given that BTG3 functions as a tumor suppressor and BTG3-KO CM and parental CM differed in their potential to promote 3T3-L1 adipogenic differentiation, we were intrigued by the possibility that the resulting adipocytes could be programmed differently for adipokine secretion." (PMID 38714880, 2024). "Surprisingly, Btg3 knockout mice appeared normal, were not susceptible to tumor formation up to 2-years of age and are fertile, suggesting that loss of Btg3 alone in mice is not tumor-prone." (PMID 33311481, 2020). "Comparative analysis showed that genes such as BTG3, PCMT1 and HK1 are gradually increasing in epithelial/malignant cells from tumor tissues compared to these cells from normal tissues." (PMID 39575251, 2024). "StromalScore and ImmunoScore were used to analyze the correlation between APRO (TOB1, TOB2, BTG1, BTG2, BTG3 and BTG4) expression and tumor purity and tumor microenvironment characteristics." (PMID 38062199, 2023). "Further, molecular experiments revealed that B-cell translocation gene 3 (BTG3) reduced upon miR-20b overexpression and led to tumor cell proliferation." (PMID 36717861, 2023). "More attractively, systemic FCANPs-mediated collaborative modulating lncRNA ASBEL/BTG3 and Cur co-delivery significantly suppressed the MDA-MB-231 xenograft tumor growth, inhibited metastasis and extended survival rate with negligible systemic toxicity." (PMID 37904215, 2023). "Importantly, we found that the effects could be mediated through non-autonomous paracrine of various pro-angiogenic and pro-inflammatory cytokines which together foster a pro-tumorigenic microenvironment; and this may partially explain the tumor suppressor role of BTG3." (PMID 33311481, 2020). "In CC cells, FBXL5 and BTG3 function as tumor suppressors and direct downstream targets of miR-20a, and the repression of FBXL5 and BTG3 can restore the invasive and resistant characteristics of CC cells, which was suppressed by iASPP or miR-20a depletion." (PMID 28399926, 2017). "BTG3 binds and suppresses AKT so as to decrease β-catenin/TCF activity, down-regulate mesenchymal markers, and consequently reduce cell migration and tumor growth." (PMID 28407690, 2017). "Although BTG3 downregulation was shown to promote expression of EMT markers and cell migration in these cells, the effects appeared insufficient to drive tumor formation in vivo, at least for U2OS cells." (PMID 25569101, 2015).
tumor (continued). "The methylation status of BTG3 in RCC was examined using human RCC cell lines A498, ACHN, HEK-293, normal kidney cell line HK-2, and 20 patient-matched tumor and adjacent normal tissue paired samples." (PMID 26198328, 2015). "The selection of A498 cells was informed by prior evidence demonstrating their responsiveness to 5-Aza-CdR-mediated demethylation and reactivation of tumor suppressor genes (e.g., WNT7A, KRT19, BTG3), confirming sufficient endogenous DNMT activity for pharmacological inhibition." (PMID 40866976, 2025). "Our findings provide a novel mechanism for the modulation of BTG3 protein levels and its function in tumor cells and the TRIM65-BTG3 interaction may play a key role in controlling the RCC cell proliferation." (PMID 38777825, 2024). "BTG3 is a member of the anti-proliferative BTG/Tob family and functions as a tumor suppressor." (PMID 38714880, 2024). "BTG3 is a member of the antiproliferative BTG/Tob (B-cell translocation gene/transducer of ErbB2) protein family, and identified as a tumor suppressor gene involved in the suppression of proliferation, cell cycle progression, apoptosis, and metastasis in various cancers." (PMID 35342408, 2022). "Some studies have found that B-cell translocation gene 3 (BTG3) is significantly downregulated in GC, which may be related to tumour proliferation, migration, and invasion, and has potential as a biomarker for predicting the prognosis of GC patients." (PMID 35923703, 2022). "Nevertheless, our study here has not only expanded the horizon controlled by the tumor suppressor BTG3 but also highlights the important role of a tumor suppressor in cell non-autonomous control of tumor progression." (PMID 33311481, 2020). "Immunohistochemical staining for the endothelial marker von Willebrand factor (vWF) demonstrated that blood vessel formation was significantly reduced in BTG3-overexpressed tumors, thus supporting a negative regulatory role of BTG3 on tumor angiogenesis." (PMID 33311481, 2020). "FBXL19-AS1 might act as the inducible endogenous RNA of hsa-miR-20b-5p to influence the expression of BTG3, KIF23, RBBP7, and TRIM37 and regulate tumorigenesis, Wnt/β-catenin pathway, tumor metastasis as well as apoptosis." (PMID 33344260, 2020). "Taken together, our findings highlight the non-autonomous regulation of tumor microenvironment by BTG3 while suppressing tumor progression." (PMID 33311481, 2020). "Since PTEN, WNK2, SOX6, BTG3, and RBSP3 have putative miR-18a-binding sites in their 3′-UTRs and act as tumor suppressors in CC, we hypothesized that miR-18a enhances PD-L1 expression via targeting these candidate targets." (PMID 29855617, 2018). "Moreover, the results from clinical samples revealed that the BTG3 expression was significantly downregulated in tumor tissues compared with adjacent nontumor tissues." (PMID 35342408, 2022). "The tumor suppressor activity of BTG3 could be attributed to interaction with and negative regulation of AKT, which is frequently deregulated in cancers." (PMID 33311481, 2020). "Although our PC3 xenograft study showed that BTG3 could be a tumor suppressor, a reciprocal knockdown in U2OS cells failed to promote xenograft tumors (data not shown)." (PMID 25569101, 2015). "Moreover, TRIM65 overexpression can only regulate the anti-tumor effect of BTG3 rather than BTG3 K41R, indicating that TRIM65-regulated BTG3 ubiquitination and degradation are critical for its function in RCC." (PMID 38777825, 2024).
cancer (36 papers, 2012 to 2025). A tumor composed of atypical neoplastic, often pleomorphic cells that invade other tissues. "BTG3 expression was positively linked to carcinogenesis, histogenesis, and aggressive behaviors, and was employed to evaluate the prognosis of cancers by regulating cell cycle, metabolism, splicing and translation of RNA." (PMID 36186486, 2022). "In TCGA, BTG3 expression was positively associated with a high overall survival rate of cancer patients (p < 0.05)." (PMID 36186486, 2022). "In this study, we identified HIF-1α as a target of regulation by BTG3 and elucidated the underlying mechanism and the implications on progression of human cancers." (PMID 33311481, 2020). "According to the previous studies, the overexpression of BTG3 using an expression vector can cause a significant decrease in the proliferation rate in cancer cell lines." (PMID 34466474, 2019). "While downregulation of BTG3 expression is associated with enhanced cell proliferation, growth, and migration, overexpression of BTG3 is associated with suppressed proliferation, reduced cancer invasiveness, and cellular apoptosis in primary cancers and cancer cell lines." (PMID 36232644, 2022). "Notably, several factors that were increased more than 2-fold, including SCF-1, VEGF, osteopontin, MCP-2/3, IL-3, IL-12, and IFN-γ, have all been implicated in various aspects of cancer development, and thus represent a unique signature of the secretome of BTG3-depleted normal human fibroblasts." (PMID 33311481, 2020). "RNA-seq analysis comparing parental and BTG3-KO HaCaT cells revealed elevated expression in BTG3-KO cells of several signature genes, such as fibronectin and AKT3, which have been implicated in cancer cell migration and metastasis." (PMID 38714880, 2024). "It has been reported that the knockdown of BTG3 in cancer cells can lead to an accelerated exit from DNA damage-induced G2/M block." (PMID 38777825, 2024). "Very similar to miR20b-5p, miR106b-5p has also been shown to be upregulated in LC and to directly play a role in the downregulation of BTG3, leading to the inhibition of cancer cell apoptosis and promoting cell proliferation." (PMID 39766101, 2024). "KEGG and PPI (protein-protein interaction) analysis showed that the BTG3 was involved in cell cycle and DNA replication, digestion and absorption of fat and protein, spliceosome and ribosome in cancer." (PMID 36186486, 2022). "Here, we aimed to clarify the clinicopathological and prognostic significances, and related signal pathways of BTG3 mRNA expression in cancers by a bioinformatics analysis." (PMID 36186486, 2022). "According to Kaplan-Meier plotter, we found that a higher BTG3 expression was negatively correlated with overall, progression-free, post-progression, and distant-metastasis-free survival rates of all cancer patients (p < 0.05)." (PMID 36186486, 2022). "According to Kaplan-Meier plotter, we found that a higher BTG3 expression was positively correlated with overall and progression-free survival rates of all cancer patients, even stratified by gender and Her2+ expression (p < 0.05)." (PMID 36186486, 2022). "ER (estrogen receptor)- positive or Her2-negative cancer patients with high BTG3 expression showed a shorter overall survival time than those with its low expression (p < 0.05, data not shown)." (PMID 36186486, 2022). "All, female T1, T2, or N1 cancer patients with high BTG3 expression showed a short progression-free survival time than those with its low expression (p < 0.05, data not shown)." (PMID 36186486, 2022). "According to the Xiantao database, the BTG3-correlated genes in cancers were analyzed and subjected to the KEGG analysis." (PMID 36186486, 2022). "On the Xiantao platform, we found the differential genes between low and high expression groups of BTG3 mRNA in cancers." (PMID 36186486, 2022). "BTG3 is a driver gene for regulating the cell cycle, apoptosis, and invasion in various cancer types." (PMID 35045800, 2022).